FOXQ1 (forkhead box Q1)
Diseases named in the same sentence as FOXQ1 in open-access papers (continued):
Sharing a sentence is not in itself a finding about the gene and the disease.
cancer (88 papers, 2012 to 2025). A tumor composed of atypical neoplastic, often pleomorphic cells that invade other tissues. "In these cancers, high FOXQ1 expression was found to be associated with a more favorable clinical outcome." (PMID 40630951, 2025). "In these cancers, high FOXQ1 expression was found to be associated with more favourable clinical outcomes." (PMID 39777582, 2025). "Luo and colleagues reported that patient-derived cancer-associated fibroblasts (CAF) increased the abundance of FOXQ1 in HCC cell lines." (PMID 39777582, 2025). "Across multiple studies, the induction of FOXQ1 in cell lines derived from different types of cancer caused morphological changes as well as increased cell motility, consistent with EMT, whereas FOXQ1 depletion had the opposite effect." (PMID 39777582, 2025). "FOXQ1 can also apparently act as a tumor suppressor in certain types of cancers, and its loss in these cancers results in a worse prognosis." (PMID 40630951, 2025). "Apart from the direct regulation of cadherin expression, induction of FOXQ1 in cancer cells is associated with an increase of other EMT markers such as vimentin and fibronectin; however, it is likely that these effects are indirect." (PMID 39777582, 2025). "We have reviewed the biological functions and pathogenic mechanisms of FOXQ1 in multiple malignant tumors, so exploring it’s necessary to explore its precise function and mechanism in the immune and inflammation system is necessary." (PMID 41347087, 2025). "FOXQ1 levels can also be increased through other cancer-associated signalling pathways, such as FGF and TGF-β signalling." (PMID 39777582, 2025). "It should be noted that several FOX genes were highly mutated in certain cancer types despite that their overall mutation rates were rather modest, such as FOXQ1, which was particularly extensively mutated in BLCA." (PMID 37401400, 2023). "The findings of FOXQ1-SIRT4-GDH axis in the control of glutamate dehydrogenase mediated α-ketoglutaric acid production in senescence and aging in this study thus point to possible metabolic abnormalities associated with FOXQ1 overexpression in cancers." (PMID 37516739, 2023). "FOXQ1 is a transcription regulator that controls the cell cycle, cell proliferation and is associated with cancers, and that inhibits macrophage recruitment, and activates Wnt signaling." (PMID 35215967, 2022). "This joint analysis of FOXQ1 at different levels is the first to be conducted using pan-cancer expression, survival, and mutation data from TCGA, Oncomine, and CCLE databases." (PMID 36118871, 2022). "Although rarely has FOXQ1 been directly associated with radio-resistance in cancers, a number of studies have indicated the correlation between FOXQ1 and cancer stem cells." (PMID 35183223, 2022). "Considering the implicated role of FOXQ1 in a vast number of cancers and biological processes, the foxq1a and foxq1b null mutants from this study provide useful genetic models to further investigate FOXQ1 functions." (PMID 29534099, 2018). "Considering the implicated role of FOXQ1 in a vast number of cancers and biological processes, the foxq1a and foxq1b mutants generated in this study provide new genetic models to further dissect the functions of FOXQ1." (PMID 29534099, 2018). "The next closest gene is forkhead box Q1 (FOXQ1) which is a member of the cancer-associated forkhead-box (FOX) gene family." (PMID 29236708, 2017). "In contrast to loss-of-function assays, overexpression of FOXQ1 enhanced cancer cell migration and invasion in PANC-1 cells." (PMID 29050264, 2017). "Prototype-based gene coexpression and gene set enrichment analysis showed a significant association between FOXQ1 and the Wnt pathway in tumors and cancer cell lines from different tissues." (PMID 23555880, 2013). "Why are high FOXQ1 levels associated with improved survival in some cancers?" (PMID 39777582, 2025).
cancer (continued). "FOXQ1 has been linked to the malignant process in a number of cancers." (PMID 37875474, 2023). "Western blotting and RT-qPCR analyses suggested that knockdown of FOXQ1 led to decreased p21 expression, while p16 remained unchanged, in line with the transcriptional association between FOXQ1 and p21 in cancer cells." (PMID 37516739, 2023). "Our results comprehensively summarize the FOXQ1 expression profile at tissue and cell levels and the association of its expression with prognosis, clinicopathological characteristics, cancer-related pathways, TMB, MSI, TME, immune cell infiltration, and immune-related genes." (PMID 36118871, 2022). "Association of forkhead box Q1 expression with cancer-related pathway." (PMID 36118871, 2022). "In conclusion, this study is the first to prove that FOXQ1 expression is closely associated with prognosis, clinicopathological parameters, cancer-related pathways, TMB, MSI, TME, immune cell infiltration, and immune-related genes via TCGA, Oncomine, and CCLE databases." (PMID 36118871, 2022). "Furthermore, Foxq1 was also involved in epithelial-mesenchymal transition regulation by suppressing E-cadherin transcription, and associated with aggressive cancer phenotype." (PMID 25098939, 2014). "Furthermore, FoxQ1 is also involved in epithelial-mesenchymal transition regulation by suppressing E-cadherin transcription and is associated with aggressive cancer phenotype." (PMID 23383267, 2013). "Taken together, these findings outline a dual role of FOXQ1 in cancer: in most types of cancer, especially carcinomas, FOXQ1 is induced and promotes disease progression." (PMID 39777582, 2025). "In light of these findings, it appears that part of its function in cancer is the stabilisation of FOXQ1, which would be interesting to explore further." (PMID 39777582, 2025). "Taken together, these studies indicate that the expression and stability of FOXQ1 are tightly controlled on multiple levels, and suggest possible explanations for the tissue-specific induction of FOXQ1 in cancer." (PMID 39777582, 2025). "Although FOXQ1 has been validated as an oncogene, its downstream targets and the signaling pathways it modulates are governed in a cancer-type-specific manner." (PMID 41347087, 2025). "Mitchell and colleagues observed that FOXQ1 binds to RBBP5 in different types of cancer cells, and that it recruits the KMT2A/MLL1 catalytic subunit to the promoters of EMT-associated genes, thereby inducing their transcription." (PMID 39777582, 2025). "In this review article, I summarise new evidence on the role of FOXQ1 in cancer, with a focus on molecular mechanisms that control FOXQ1 levels and the regulation of FOXQ1 target genes." (PMID 39777582, 2025). "While the contribution of FOXQ1 to normal physiology and tissue homeostasis appears to be limited, this transcription factor has gained considerable attention in the context of cancer biology." (PMID 39777582, 2025). "FOXQ1 promotes cancer aggressiveness, such as cell proliferation, migration, and invasion in vitro, as well as growth in vivo, through the activation of the FAK/PI3K/AKT signaling pathway." (PMID 41347087, 2025). "Collectively, FOXQ1 appears to regulate converging angiogenic transcriptional programs that allow cancer cells to connect to the circulation and thereby disseminate to remote locations in the body." (PMID 39777582, 2025). "Neovascularisation can occur either through the recruitment of endothelial cells or vascular mimicry of the cancer cells themselves, and both of these processes are controlled by FOXQ1 as well." (PMID 39777582, 2025).
cancer (continued). "Although this study did not explore the connection between FOXQ1 and Wnt signalling in detail, it seems that the Wnt-dependent regulation of FOXQ1 levels has important implications beyond the biology of cancer." (PMID 39777582, 2025). "FOXQ1 expression is silenced in most adult tissues, yet its transcription is frequently induced in cancers." (PMID 39777582, 2025). "Subsequent studies confirmed and expanded on these findings, showing that altered expression of FOXQ1 can be observed in numerous types of cancer." (PMID 39777582, 2025). "Are there any specific FOXQ1 target genes, or is its role in cancer redundant with other FOX family members?" (PMID 39777582, 2025). "Cancers with increased FOXQ1 levels include, especially, carcinomas of the colon, but also epithelia-derived cancers of the lung, the stomach, the pancreas, and the oesophagus." (PMID 39777582, 2025). "Shortly after its initial discovery as a possible oncogene, several groups independently reported that FOXQ1 promotes EMT in various types of cancer cells." (PMID 39777582, 2025). "The forkhead box (FOX) family transcription factor FOXQ1 is a putative carcinoma oncogene that is highly induced in several types of cancer." (PMID 38432629, 2024). "A pan-cancer investigation revealed that the expression of FOXQ1 was connected to the activation and inactivation of 33 pathways in 12 tumors." (PMID 37875474, 2023). "FOXQ1 has been reported to regulate Wnt/β-catenin signaling, a key pathway involved in cancer progression." (PMID 38062011, 2023). "Both the overactivated FGFR1 signaling and the overexpressed FOXQ1 are oncogenic factors that promote the proliferation, invasiveness, and progression of cancer cells 3-5, 21-26." (PMID 36778115, 2023). "Our findings corroborate previous studies that revealed the up-regulated expression of FOXQ1 and its cancer metastasis-promoting effects in CRC." (PMID 35183223, 2022). "Results of ChIP assay then showed that the enrichment level of FOXQ1 in cancer tissues in SIRT1 promoter region was much higher than that in adjacent normal tissues." (PMID 35183223, 2022). "These cell type-dependent observations suggest a critical need to understand the epigenetic contexts governing FOXQ1 function in cancer." (PMID 36319643, 2022). "Second, specific small molecular inhibitors can be developed to interrupt FOXQ1-RbBP5 interaction to nullify FOXQ1 function in cancer progression." (PMID 36319643, 2022). "The correlation of FOXQ1 expression with cancer-related pathway activity was explored to determine the potential mechanism of FOXQ1 in pan-cancer." (PMID 36118871, 2022). "The upregulation of SIRT1 by for Forkhead Box Q1 (FOXQ1) contributes to CRC survival inducing cancer cell radio-resistance and cell stemness." (PMID 35328633, 2022). "Mir–506–3p was down–regulated in cancer cells, a key miRNA regulating FoxQ1, leading to increased FoxQ1 expression, which in turn resulted in the production of CCL2 and ultimately promoted macrophage recruitment." (PMID 36059616, 2022). "Cumulative studies indicated that FOXQ1 is capable of promoting metastasis in diverse cancers, especially in CRC." (PMID 33639954, 2021). "FOXQ1 was also reported to positively regulate several other genes involved in cancer invasion and metastasis, such as Snail39 and LAMA437." (PMID 32332873, 2020).
cancer (continued). "It has since been revealed that FOXQ1 functions as an oncogene in many human cancer types, including BCa." (PMID 33098639, 2020). "We also evaluated the effects of FOXQ1 expression on Twist1, which has been established as a direct target of FOXQ1 in cancers including CRC." (PMID 33330033, 2020). "FOXQ1 is an established modulator of Twist1 expression and a regulator of cancer invasion and metastasis in CRC, and the role of Twist1-induced CCL2 in angiogenesis has been previously demonstrated." (PMID 33330033, 2020). "Recently, a number of studies revealed the implication of FOXQ1 in cancer progression and metastasis." (PMID 32332873, 2020). "Through a series of functional experiments, we illustrated that miR-4319 repressed cell proliferation, accelerated apoptosis, inhibited epithelial-mesenchymal transition (EMT) and prevented cancer stemness in HCC cells by targeting FOXQ1 (Forkhead box Q1)." (PMID 31853229, 2019). "It is well-established that CCL2 is a chemokine that is essential for the recruitment of macrophage cells, and FoxQ1 expressed in cancer cells has shown to increase attraction of macrophages through CCL2 production." (PMID 30927925, 2019). "On the basis of our data and previous studies, we proposed that FoxQ1 expressed in cancer cells was closely involved in development of the TME by inducing invasion, metastasis, and chemotactic activity." (PMID 30927925, 2019). "Herein, we demonstrated that the level of miR-4319 was remarkably decreased in HCC specimens and cells and that miR-4136 induced inhibition of the epithelial-mesenchymal transition and prevented cancer stemness of HCC through targeting FOXQ1." (PMID 31853229, 2019). "FOXQ1 is a member of the forkhead-box transcription factor family that has important functions in development, cancer, aging, and many cellular processes." (PMID 29534099, 2018). "Establishing a function for FOXQ1 in innate immune regulation can provide new understanding of its role in various cancers." (PMID 29534099, 2018). "The role of FOXQ1 in cancer biology has raised intense interest, yet much remains poorly understood." (PMID 29534099, 2018). "Numerous studies have demonstrated that FOXQ1 (as well as other FOX-family member) is associated with the progression, metastasis and drug resistance of human cancers." (PMID 29050264, 2017). "Previous studies have alsodescribed a key role for FOXQ1 in regulatingEMT and aggressiveness in human cancer." (PMID 28580309, 2017). "Past studies showed that aberrant expressed FOX-family of transcription factors were involved in several types of cancers, however, functional significance of FOXQ1 in PDAC is still unclear." (PMID 29050264, 2017). "Three genes (SOX4, FOXM1, and FOXQ1) were subsequently chosen for further investigation based on their known role in colorectal or other human cancer types." (PMID 27119506, 2016). "It has also been reported that FOXQ1 expression is essential for maintaining cancer cell proliferation, motility, invasion, and epithelial-mesenchymal transition in epithelial ovarian cancer." (PMID 27703207, 2016). "In view of a plausible biological function of FOXQ1 in promoting cancer aggression, as well as marginal statistical significance that was a likely consequence of small sample size, rs11242675 was included in the GRS for risk assessment." (PMID 24941967, 2014). "We found that the average expression level of Foxq1 was up-regulated in NPC tissue compared with non-cancer biopsy samples." (PMID 25098939, 2014). "Our data also showed that the Foxq1 expression was statistically higher than in non-cancer biopsy samples." (PMID 25098939, 2014). "In summary, we showed for the first time the molecular events underpinning the increased expression of FOXQ1 in cancers, and show the usefulness of FOXQ1 as a marker for Wnt activity in cancer cell lines." (PMID 23555880, 2013).
cancer (continued). "Through the use of public available expression data sets we have examined the expression of FOXQ1 in solid tumors and cancer cell lines." (PMID 23555880, 2013). "For the first time we demonstrate that FOXQ1 is a direct Wnt target and the expression level correlates with the overall expression of Wnt genes in cancer biopsies and cell lines, thus, demonstrating its potential as a marker for Wnt activation." (PMID 23555880, 2013). "FoxQ1 protein levels were upregulated in 5 of 6 malignant tumor samples, whereas NRXN3 protein levels were downregulated in the 5 malignant tumor samples." (PMID 23383267, 2013). "Forkhead box Q1 (FoxQ1) is a member of the forkhead transcription factor family, and it has recently been found to participate in cancer development." (PMID 23383267, 2013). "In this study, using microarray data from cancer cell lines and patient samples, and molecular biological techniques we examined the relationship between FOXQ1 and the Wnt pathway." (PMID 23555880, 2013). "Focusing on carcinoma cell lines derived from colon, breast, lung, pancreas and stomach FOXQ1 ranked best in terms of correlation with the mean expression of all Wnt targets suggesting it to be a suitable and sensitive marker for Wnt activation in cell lines." (PMID 23555880, 2013). "EMT is also promoted by the FOXQ1, another up-regulated gene in cancer cells grown under co-culture conditions with the CAFs." (PMID 22453032, 2012). "The role of the forkhead box Q1 (FOXQ1) transcription factor in cancer pathogenesis has recently emerged." (PMID 23203039, 2012). "Human FOXQ1, located on chromosome 6p23-25, has been isolated and characterized and plays an essential part in the aetiology of human cancer." (PMID 22761930, 2012). "The results obtained from our data are in accordance with those presented in the emerging literature, which had declared that the repression of FoxQ1 led to an increase in E-cad expression in human carcinoma." (PMID 22761930, 2012). "Although these authors investigated the role of USP10-dependent regulation of FOXQ1 in the context of acute kidney injury, these findings may have implications for cancer biology as well." (PMID 39777582, 2025). "It is therefore worthwhile to consider if FOXQ1 could be targeted for the treatment of cancers, especially since evidence from knock-out mice suggests that FOXQ1 is largely dispensable for normal tissue homeostasis in the adult organism." (PMID 39777582, 2025). "This suggests that FOXQ1's essential role in quiescent brain endothelium centers on maintaining cellular bioenergetic function rather than driving the dynamic morphological changes characteristic of cancer progression." (PMID 40884816, 2025). "These discoveries open up several possible avenues for targeting FOXQ1 in cancer, which could lead to the development of new drugs for the treatment of cancers." (PMID 39777582, 2025). "Treatment of colorectal and mammary epithelial cell lines with TGF-β induced FOXQ1 expression, suggesting that FOXQ1 may be a downstream effector of this cytokine in cancer cells." (PMID 39777582, 2025). "Collectively, these observations highlight important interactors of FOXQ1 that may be critical for its function in cancer cells." (PMID 39777582, 2025). "FOXQ1 regulates the expression of angiogenic factors such as VEGF, CCL2, and ANGPT1 in cancer cells, and consistently, conditioned media from FOXQ1-expressing cells are sufficient to enhance angiogenesis and blood vessel formation by endothelial cells in vitro." (PMID 39777582, 2025). "Going forward, it will be of considerable interest to determine if these interactors are specific for FOXQ1, whether these interactions are dependent on the type of cells, and how these interactions can be targeted for the treatment of cancers." (PMID 39777582, 2025).